METTL3 (methyltransferase 3, N6-adenosine-methyltransferase complex catalytic subunit)
Diseases named in the same sentence as METTL3 in open-access papers (continued):
Sharing a sentence is not in itself a finding about the gene and the disease.
cancer (724 papers, 2017 to 2026). A tumor composed of atypical neoplastic, often pleomorphic cells that invade other tissues. "For example, overexpression of METTL3 has been associated with enhanced DNA repair capacity in cancer cells, leading to resistance against genotoxic therapies such as chemotherapy and radiation." (PMID 40760453, 2025). "In present study, METTL3 was identified as an authentic manipulator of cilia assembly and elongation associated with cancer development." (PMID 39535388, 2025). "METTL3 induces the upregulation of splicing factors, whereas METTL3 deficiency affects the translation of splicing factors, which leads to splicing dysregulation and affects cancer development." (PMID 40356985, 2025). "In CRC, METTL3‐dependent m6A methylation upregulates miR‐181b‐5p in Cancer‐Associated Fibroblasts (CAFs), reducing 5‐FU sensitivity." (PMID 39802639, 2025). "Methyltransferase‐like 3 (METTL3), a key enzyme involved in m6A methylation, has been implicated in the development and progression of various cancers, including EC." (PMID 39980152, 2025). "Ongoing research, including clinical trial NCT05584111, is exploring the potential of targeting m6A-associated proteins, particularly METTL3, for therapeutic interventions against advanced cancers." (PMID 40214229, 2025). "The Cancer Genome Atlas (TCGA) database revealed a very low mutation rate, minimal frequency of METTL3 loss or gain, and negligible changes in its mRNA levels in both GBM and LGG." (PMID 41321637, 2025). "Accumulating evidence indicates that METTL3 overexpression is implicated in the initiation and metastasis of various types of cancer." (PMID 40651967, 2025). "In this study, we found an upregulation of METTL3 in various cancers, including NPC, which is associated with poor survival." (PMID 39990661, 2025). "METTL3-mediated downregulation of SRSF11 expression was associated with poor prognosis in these cancers." (PMID 39767561, 2024). "Aberrant m6A modification profiles and abnormal expression of METTL3 have been associated with the initiation and progression of different types of cancers." (PMID 38233403, 2024). "For example, in hepatic cancer, the stabilization and subsequent upregulation of LINC00958, facilitated by METTL3-mediated m6A modification, has been implicated in advancing cancer progression." (PMID 38255219, 2024). "TCGA pan-cancer correlation analysis revealed a significant positive association between METTL3 and LINC01106 in BCa samples." (PMID 38255219, 2024). "In recent years, mRNA m6A methylation mediated by the METTL3–METTL14 complex has offered a novel paradigm for elucidating the mechanisms underlying cancer progression." (PMID 38965238, 2024). "The dysregulation of m6A, notably the upregulation of METTL3, has been associated with a range of cancers." (PMID 38809498, 2024). "Given the identification of an association between altered METTL3, m6A, and cancer development, progression, and therapy resistance, there is considerable interest in METTL3 as a novel cancer therapeutic target." (PMID 39033689, 2024). "STM2457, a novel small molecule inhibitor specific for N6-methyladenosine (m6A) catalytic enzyme Methyltransferase-like 3 (METTL3) has implicated significant treatment potentials in a few of types of cancer." (PMID 39132158, 2024). "The ability of these compounds to reactivate METTL3 to suppress cancer subtypes associated with METTL3 downregulation remains to be explored." (PMID 38545841, 2024). "It is worthy of note that METTL3 dysregulation is closely associated with the emergence of various diseases ranging from a variety of malignant tumors to immunological and metabolic diseases." (PMID 38545555, 2024). "Targeting these pathways, especially through METTL3, offers promising therapeutic strategies to combat drug resistance in cancer cells carrying this mutation." (PMID 39329012, 2024).
cancer (continued). "By modifying the methylation of circular RNA (circRNA), long noncoding RNA (lncRNA), and transcripts of other cancer-associated genes, METTL3 is involved in the progression of HCC by regulating the stability of related RNAs." (PMID 39229278, 2024). "By depositing m6A modifications on mRNA molecules, METTL3 ensures the proper stability and integrity of these transcripts, ultimately influencing important cellular processes associated with cancer development and progression." (PMID 38390305, 2024). "Downregulation of m6A modification caused by METTL3 deficiency significantly impairs cancer cell migration, invasion, and EMT process." (PMID 39473440, 2024). "Since the m6A mark is most abundant in human RNA and METTL3-METTL14 upregulation is a hallmark of cancer, some biotech companies have already developed METTL3 inhibitors." (PMID 39459530, 2024). "Elevated expression of METTL3 in CRC tissues has been associated with lower survival rates during cancer metastasis." (PMID 39295872, 2024). "METTL3 is the main catalytic component of the m6A methyltransferase complex and is associated with chemoresistance in many cancer types." (PMID 39661414, 2024). "METTL3 can upregulate the expression of the cancer promoting lncRNA metastasis associated lung adenocarcinoma transcript 1 (MALAT1) to promote EMT, migration and BC infiltration." (PMID 38711100, 2024). "In TCGA datasets, METTL3 is overexpressed in a variety of cancers and shows high mutations in bladder cancer (BCA), endometrioid cancer (EOC) and colon cancer." (PMID 36260366, 2023). "To understand the association of METTL3 expression and immune cell infiltration in cancers, we utilized the TIMER database." (PMID 38012755, 2023). "As the major RNA m6A writer, the expression of METTL3 is closely associated with the genesis and development of cancers." (PMID 36260366, 2023). "In cancer-associated biological processes, METTL3, the most important subunit of the methyltransferase complex, has been reported to promote the hypoxic tolerance, drug resistance, immune response and EMT in multiple cancer cells." (PMID 37095108, 2023). "The m6A writer METTL3 has been proved to be associated with cancer progression in a variety of cancer types." (PMID 36300630, 2023). "Considering the function of METTL3 on RNA modification, the RNA m6A level in cancer cells with METTL3 deficiency was investigated through dot blot." (PMID 38001065, 2023). "Previous studies have implicated METTL3 as a potential therapeutic target in multiple cancer types by influencing RNA surveillance, and protein translation." (PMID 38012755, 2023). "METTL3 was confirmed to inhibit the sensitivity through miR181b5p in cancer-associated fibroblasts (CAFs) secreted exosomes." (PMID 36810281, 2023). "Abnormal m6A modification levels caused by METTL3 have been identified as critical regulator in human cancers." (PMID 36835633, 2023). "Differentially expressed and spliced genes in METTL3 knockdown MCF7 cells were enriched in cancer-associated categories such as MAPK cascade, cell migration and cell-cell adhesion." (PMID 36725888, 2023). "The comprehensive analysis conducted in this report evaluated the expression, prognostic value, methylation level, immunology, and signaling pathways associated with METTL3 in various cancer types." (PMID 38012755, 2023). "Current evidence suggests that the dysregulation of METTL3-mediated m6A methylation modification is closely associated with cancer progression." (PMID 37231451, 2023). "Multiple types of immune cells have been suggested to be associated with METTL3 expression in various cancers, especially T cells." (PMID 36614956, 2022). "Conspicuously, METTL3 will be realized as a hallmark for cancer initiation and propagation and deserve appreciation." (PMID 35090469, 2022). "High expression of METTL3 promotes cancer development and is associated with poor prognosis in these cancers." (PMID 36232485, 2022).
cancer (continued). "Correlation analyses showed that the expression levels of METTL3 were positively associated with those of DNA MMR genes in almost all types of cancers." (PMID 36614956, 2022). "Accumulating evidence has identified that METTL3 is implicated in human cancers either as an oncogene or a cancer suppressor in recent years." (PMID 35280730, 2022). "For instance, METTL3-mediated m6A controlled TGF-β-induced epithelial-mesenehymal transition (EMT) in cancer cells, and obviously suppressed lung metastasis in vivo in response to METTL3 deficiency." (PMID 35046996, 2021). "We found that high expression level of METTL3 associated with several cancer‐related biological processes, including mitotic spindle formation, G2‐M checkpoint signaling, and E2F targets signaling pathway." (PMID 34668652, 2021). "METTL3 was also associated with several cancer‐related cellular processes, including mitotic spindle assembly, G2/M checkpoint, and E2F targets signaling pathway." (PMID 34668652, 2021). "Further investigations on the underling mechanisms and targeted inhibitors of METTL3 are of great significance for deeper understanding of the relationship between m6A modification and human cancer." (PMID 33879256, 2021). "Three subunits of the eukaryotic initiation factor 3 (eIF3) complex are correlated with cancer development—subunit eIF3d possesses cap-binding activity; eIF3G is associated with cancer progression; eIF3h interacts with METTL3." (PMID 33808751, 2021). "Methyltransferase-like 3 (METTL3) is a m6A methylase closely implicated in cancer biogenesis and development." (PMID 34497267, 2021). "Abnormal m6A levels caused by METTL3 have been reported to be involved in different aspects of cancer development, including proliferation, apoptosis, and metastasis." (PMID 32429972, 2020). "In terms of function, these METTL3-correlated miRNAs were enriched in several cancer-associated pathways, such as cell proliferation, immunity, AKT pathway, onco-miRNA, angiogenesis, apoptosis, and cell cycle." (PMID 33037176, 2020). "High expression of the “writer” METTL3 is associated with poor prognosis of patients with several cancers, including HCC, AML, and glioma." (PMID 32296573, 2020). "Studying the upstream regulatory mechanism of METTL3 caused by epigenetic modification will allow us to better understand the biological function of METTL3 in cancers." (PMID 32429972, 2020). "METTL3 is an RNA methyltransferase implicated in the control of cell differentiation and proliferation in embryonic development and cancer." (PMID 32068977, 2020). "ZC3H13 was upregulated in patients with high cancer risk, whereas METTL3, KIAA1429, YTHDF1, and YTHDF2 were downregulated." (PMID 32631107, 2020). "Elevated expression of METTL3 was detected in lung cancer cells, which was associated with cancer cell growth, survival, and invasion." (PMID 32854717, 2020). "METTL3 is implicated in many aspects of human cancer cell progression, which has prompted many researchers to explore its possible molecular mechanism." (PMID 31921660, 2019). "We experimentally validated the functional relevance of somatic mutations in METTL3, providing further support for both the effectiveness of our method, and for the potential importance of RNA methylation in cancer." (PMID 31363082, 2019). "In this review, we summarized the recent advances made in relation to METTL3 dysregulation and its dual role coupled with the underlying mechanisms in various human cancers." (PMID 31921660, 2019). "Nevertheless, more studies are needed to explore whether other m6A-related genes are associated with the radiosensitivity of HCC and whether METTL3/IGF2BP2 can predict the radiosensitivity of pan-cancer." (PMID 39799112, 2025). "Our findings extend this concept by proposing that modulating O-GlcNAc modification could serve as a viable approach to regulate METTL3 levels and influence ferroptosis, a form of regulated cell death implicated in cancer biology." (PMID 40495163, 2025).
cancer (continued). "Additionally, METTL3 has been implicated in resistance to various therapies across different cancer types." (PMID 39472692, 2025). "Interestingly, the thyroid tissue derived from Mettl3 KO mice showed normal thyroid follicle loss instead of exhibiting closely arranged cancer cells, even in 5-week-old mice." (PMID 38993572, 2024). "In addition to cancer, METTL3 has been linked to various other diseases, including obesity, diabetes, cardiovascular disease, and immune disorders." (PMID 39728691, 2024). "Also, METTL3 deficiency significantly increased cancer stem cell markers’ surface expression in all studied cell lines." (PMID 38966069, 2024). "For instance, aberrant methylation patterns have been implicated in various cancers, and targeting the PTMs of METTL3 could restore normal mRNA methylation and gene expression profiles." (PMID 39416774, 2024). "KEGG enrichment of these DEGs indicated that METTL3 was negatively associated with protein processing in endoplasmic reticulum, while favorably connected to various cancer-related pathways, such as HIF-1 signaling, endocrine resistance, FoxO signaling, and proteoglycans." (PMID 37675218, 2023). "METTL3 is an important methylation enzyme that is associated with cancer progression." (PMID 38117350, 2023). "Moreover, a previous meta-analysis including 9 studies showed that high METTL3 expression was associated with poor prognosis in cancer patients, and the expression of METTL3 in included 9 studies were all detected by qRT-PCR." (PMID 36347025, 2022). "Besides, METTL3 promoted the exosomal miR-181b-5p in cancer-associated fibroblasts (CAFs) and suppressed CRC cell sensitivity to 5-fluorouracil (5-FU) via the METTL3/miR-181d-5p axis." (PMID 36517820, 2022). "Finally, control over METTL3/METTL14 condensation is determined by its small molecule cofactor, S-adenosylmethionine (SAM), which regulates conformations of two gate loops, and some cancer-associated mutations near gate loops can impair METTL3 condensation." (PMID 35143475, 2022). "This suggests that METTL3 regulates the normal splicing and function of cancer-associated genes." (PMID 36291932, 2022). "In addition to mRNAs, METTL3 has been associated with long non-coding RNAs (lncRNAs) in cancers including HCC." (PMID 34046411, 2021). "The depletion of METTL3 is known to cause apoptosis of cancer cells and may reduce their invasiveness, while the activation of ALKBH5 by hypoxia has been shown to induce cancer stem cell enrichment." (PMID 34660259, 2021). "Recent studies showed that aberrant expression of METTL3 is associated with various cancers." (PMID 33061938, 2020). "Considering the differing results of Mettl3 and m6A in various cancer types, our study may provide the causative link between Mettl3 SUMOylation and tumorigenesis and metastasis." (PMID 32483411, 2020). "Wild-type METTL3 successfully restored the normal growth rate and somatic mutations in METTL3 may disrupt the m6A methylation process and promote cancer cell growth." (PMID 31921660, 2019). "Additionally, METTL3 is implicated in therapy resistance across cancers." (PMID 39098905, 2024). "PTMs can modulate the subcellular localization of various signaling molecules, and METTL3 itself undergoes SUMOylation, methylation, ubiquitination, phosphorylation and acetylation, being the latest one associated with nuclear-to-cytoplasmic translocation of METTL3 in cancer metastasis." (PMID 38444581, 2024). "Given the identification here of pathways enriched with differentially expressed and spliced genes associated with cancer, it is plausible that METTL3 expression is higher in PCa and associated with BCR and therefore such patients may benefit from METTL3 inhibition." (PMID 36291932, 2022). "However, METTL3 may play different roles in various cancers according to the different pathogenic and multistage carcinogenesis mechanisms of different cancer types." (PMID 36614956, 2022).
cancer (continued). "In addition, pan-cancer’s risk gene is METTL3 and the protective gene is IGF2BP1." (PMID 34957092, 2021). "Further investigation into the molecular mechanisms and clinical implications of Mettl3 in these cancers will pave the way for more effective interventions and improved patient care in the future." (PMID 41517663, 2026). "Targeted drugs, such as those targeting MYC, have shown efficacy in cancer treatment, and Mettl3 can serve as an upstream regulator of MYC." (PMID 41517663, 2026). "While METTL3 regulation in cancer has been partially characterized, its PTM‐driven control during senescence remains unexplored." (PMID 41457744, 2026). "Among these, METTL3, the core methyltransferase for m6A modification, has gradually attracted much attention due to its cancer-promoting role in multiple cancers." (PMID 41362669, 2026). "Another source of resistance stems from the presence of cancer stem cells, where METTL3 enhances drug resistance through Frizzled Class Receptor 10 (FZD10) in these cells." (PMID 40103332, 2025). "The downregulation of METTL3 can significantly increase the expression of Gli and limit cancer growth." (PMID 40136363, 2025). "Our study links nucleotide biosynthesis with RNA epigenetics in cancer progression through the PRPS2-MAT2A-WTAP/METTL3/METTL14 axis, and elucidates both enzyme-dependent and independent functions of PRPS2." (PMID 40295500, 2025). "The knockdown of METTL3 resulted in erastin-resistant cancer cells, prompting us to focus on upregulated genes in METTL3 knockdown HeLa cells." (PMID 39800682, 2025). "Although there are few reports on siRNA targeting Mettl3 in BCa, the use of siRNA delivered by nanocarriers has become a new focus in cancer therapy." (PMID 40678060, 2025). "Several METTL3/m6A-regulated miRNAs have since been characterized in various cancers, and have been shown to regulate various aspects of cancer pathology." (PMID 40338154, 2025). "METTL3 also plays a pivotal role in cancer metastasis through its regulation of the MAPK signaling pathway and related immune responses." (PMID 39802639, 2025). "It appears that m6A modification of METTL3 increases gene expression and enhances proliferative signals in cancer." (PMID 40448344, 2025). "While lactylation of the catalytic subunit METTL3 has been reported to enhance m6A deposition in cancer immunity, our study unveils a distinct regulatory mechanism centered on the regulatory subunit WTAP in the context of infection-driven MASLD." (PMID 41384837, 2025). "From a therapeutic perspective, targeting METTL3 modifications has emerged as a promising strategy in cancer treatment, given its central role in regulating RNA methylation and downstream oncogenic pathways." (PMID 40495163, 2025). "For example, Snail (an EMT-inducing transcription factor) and the growth factor TGFβ1 were previously reported to be regulated by METTL3 required for the development of cancers." (PMID 40612868, 2025). "In several cancers, Mettl3 acts as an oncogene by modulating m6A modifications of target genes, thereby controlling their expression or stability." (PMID 40765834, 2025). "Elevated METTL3/METTL14 levels have been shown to drive the growth of several cancer types, and METTL3/METTL14 inhibitors have emerged as potential therapeutic agents." (PMID 40332203, 2025). "Inhibiting METTL3 can effectively suppress cancer cell proliferation and increase the efficacy of chemotherapeutic drugs." (PMID 40747121, 2025). "For example, Mettl3 knockout in mice is embryonically lethal, whereas METTL3 is oncogenic in various cancers." (PMID 41373022, 2025). "Accordingly, METTL3 overexpression leads to an increase in the m6A activity that regulates specific genes to maintain cancer cells." (PMID 41157107, 2025). "Until 2017, there were relevant studies on the role of METTL3 as an m6A methyltransferase in human cancer." (PMID 40356909, 2025).